CDK5 (cyclin dependent kinase 5)
Diseases named in the same sentence as CDK5 in open-access papers (continued):
Sharing a sentence is not in itself a finding about the gene and the disease.
prostate carcinoma (continued). "In our previous study, we reported that Cyclin-dependent kinase 5 (CDK5), a unique member of Cyclin-dependent kinases, regulates AR activation during the development of prostate cancer." (PMID 36482936, 2022). "Our previous studies indicated that CDK5 promotes prostate cancer cell growth in vitro, in vivo, and prostate cancer patients." (PMID 34207842, 2021). "This group demonstrated that in prostate cancer cells, CDK5 directly phosphorylates the AR at Ser81." (PMID 31910742, 2020). "This clinical finding suggests that CDK5 and p35 certainly play crucial roles in the development of prostate cancer." (PMID 31395805, 2019). "In prostate cancer, CDK5 increased cell growth ability in an androgen receptor (AR)-independent manner." (PMID 31496920, 2019). "Our results demonstrated that Roscovitine treatment significantly suppressed AR protein activation, AR subcellular translocation, transcriptional activity, and cell proliferation in prostate cancer cells, which was strongly correlated to CDK5 actions." (PMID 31395805, 2019). "Taken together, our data suggest that RA as a trophic factor derived from Vitamin A induces apoptosis of prostate cancer through CDK5 overactivation." (PMID 31395805, 2019). "TLN1 S425 is phosphorylated by cyclin-dependent kinase 5 (CDK5), which controls the metastatic potential in prostate cancer." (PMID 31108958, 2019). "Our previous results indicated that CDK5 increases prostate cancer growth through the activation of AR protein and the CDK5–p35/AR complex translocates into the nucleus and promotes prostate cancer growth." (PMID 31395805, 2019). "The results demonstrated that CDK5 still promotes tumor growth under CDK2 inhibition in a prostate cancer cell line in a 22Rv1-derived xenograft model." (PMID 31395805, 2019). "Concerning prostate cancer, the androgen receptor (AR) is majorly involved in tumorigenesis, while CDK5 can phosphorylate AR and promotes the proliferation of prostate cancer cells." (PMID 31395805, 2019). "We demonstrated the expression and biological functions of CDK5, p35, and p25 in prostate cancer cells for the first time." (PMID 31395805, 2019). "The results indicated that overexpression of CDK5 and p35 decelerates the degradation of AR protein in prostate cancer cells while CDK5 overexpression cannot help the degradation of S81A mutant AR." (PMID 31395805, 2019). "These pieces of evidence imply that CDK5 is reasonably sensitive to the control of both prostate cancer survival and growth." (PMID 31395805, 2019). "Our results also showed that knockdown of CDK5 blocks RA-induced apoptosis in human prostate cancer." (PMID 31395805, 2019). "For example, CDK5 has been reported to highly express in hepatocellular carcinomas and promote tumor vessels formation though directly stabilizing the HIF-1α, and CDK5 also participated in regulating the migration of prostate cancer cells." (PMID 31311512, 2019). "Regarding prostate cancer, our previous findings with in vitro, in vivo, and clinical evidence demonstrated that CDK5 promotes prostate cancer growth through activation of various downstream signaling pathways." (PMID 31395805, 2019). "After our first demonstration of CDK5 in prostate cancer cells, we also showed that CDK5 phosphorylates AR at Ser-81 in prostate cancer cells and regulates the stabilization of AR proteins, therefore, the prostate tumor growth was promoted." (PMID 31395805, 2019). "In this review paper, we summarize the significant studies on CDK5-mediated regulation of prostate cancer cells." (PMID 31395805, 2019). "Isoform1 makes up more than 90% of the total expression of CDK5 in prostate cancer but less than 40% in benign tissues." (PMID 30367578, 2018). "It has been reported that protein CDK5 can activate and stabilize AR in the nucleus through Ser-81 phosphorylation in prostate cancer cells." (PMID 30367578, 2018).
prostate carcinoma (continued). "Especially, isoform switching of kinase gene CDK5 was found in prostate cancer and benign tissues, which suggests its regulatory role in AR phosphorylation via alternative splicing." (PMID 30367578, 2018). "We observed that CDK5 has different isoform usage between androgen-dependent and androgen-independent prostate cancer cell lines." (PMID 30367578, 2018). "These different isoform preferences of CDK5 between androgen-independent or dependent prostate cancer cell lines implies that CDK5 can modulate AR transcriptional activity through differential splicing in accordance with the present or absent of androgen." (PMID 30367578, 2018). "We inferred that the higher relative expression of CDK5 Isoform1 in cancer cells can plays an important role in AR-involved prostate cancer progression." (PMID 30367578, 2018). "This conclusion was well illustrated by the observation that the AR phosphorylation kinase gene CDK5 undergoes isoform switching between prostate cancer and benign tissues." (PMID 30367578, 2018). "Our work characterized the expression and splicing profiles of kinase genes in prostate cancer and proposed a hypothetical model on isoform switching of CDK5 and AR phosphorylation in prostate cancer." (PMID 30367578, 2018). "Among them, CDK5 was detected to undergo isoform switching between prostate cancer and benign tissues, which suggests an important regulatory role of CDK5 alternative splicing on AR phosphorylation in prostate cancer." (PMID 30367578, 2018). "We validated the CDK5 isoform expression pattern in another RNA-Seq dataset of 21 prostate cancer and benign cell lines." (PMID 30367578, 2018). "The isoform ratio change of CDK5 can act as a fine tuner of AR activity and contribute to prostate cancer progression." (PMID 30367578, 2018). "The anti-apoptosis role of Cdk5 has also been proved in thyroid cancer cells and prostate cancer cells." (PMID 28288624, 2017). "There are also reports that Cdk5 mediates prostate cancer progression through STAT3 and AR signaling." (PMID 28288624, 2017). "In prostate cancer cells exposed to retinoic acid (RA) treatment (a traditional anti-cancer drug), Cdk5 is overactivated and cell proliferation is suppressed." (PMID 28288624, 2017). "The expression of CDK5 was aberrant in several cancers, and CDK5 regulated the proliferation of cancer cell in prostate cancer, medullary thyroid carcinoma, and gastric cancer." (PMID 26860827, 2016). "In the present study we set out to identify agents that would be particularly effective in combination with CDK5 inhibition in prostate cancer cells." (PMID 24841903, 2014). "Cyclin-dependent kinase 5 (CDK5) is a potential target for prostate cancer treatment, the enzyme being essential for prostate tumor growth and formation of metastases." (PMID 24841903, 2014). "In prostate cancer cells, we demonstrated that CDK5 was critical for cytoskeletal integrity, cell migration and invasion, and in vivo, for metastasis." (PMID 24841903, 2014). "In the present study, we identified agents that target prostate cancer cells based on CDK5 expression." (PMID 24841903, 2014). "Here, we performed a similar JHDL screening with prostate cancer cells which differ in CDK5 activity." (PMID 24841903, 2014). "CDK5 activity was suppressed by transfection of PC3 prostate cancer cells with a dominant-negative construct (PC3 CDK5dn)." (PMID 24841903, 2014). "Specifically, we found that protein stability of androgen receptor is regulated by physiological activation of Cdk5 in prostate cancer cells and cell proliferation is, therefore, promoted." (PMID 23304206, 2012). "In this study, we demonstrate the mechanism that how RA triggers apoptosis of androgen-independent prostate cancer cells, in which, we emphasize the importance of p25/Cdk5 deregulation in RA-triggered apoptosis in DU145 cells." (PMID 23304206, 2012).
prostate carcinoma (continued). "Regulation of CDK5 depends on its activator p35, the expression of which increases in aging cells and tumor cells (osteosarcoma, prostate cancer, colorectal cancer) and is required for the activation of CDK5 induced by pRB during the unfolding of the senescence program." (PMID 40725041, 2025). "In addition, we used the ScircRNA inhibiting CDK5 expression to trigger T-cell mediated cancer immunotherapy for treating prostate cancer in vivo." (PMID 39959665, 2025). "As observed in prostate cancer, CDK5 also phosphorylates STAT3 at S727 in MTC cells." (PMID 37993880, 2023). "Finally, CDK5 also shows significant crosstalk with the PI3K-Akt cascade in prostate cancer cell proliferation since CDK5 seems to physically interact with Akt to control Akt membrane sequestration and androgen receptor-mediated activation." (PMID 36791155, 2023). "Thus, CDK5 is frequently deregulated in prostate cancer, and its levels strongly correlate with poor clinical prognosis." (PMID 37993880, 2023). "In particular, the high enzymatic activity of CDK5 was also confirmed in liver and prostate cancer." (PMID 33396266, 2020). "Besides, it has been reported that p35 can translocate into the nucleus in prostate cancer cells and possibly regulates nuclear CDK5 and AR activation." (PMID 31395805, 2019). "Thus, CDK5 plays a crucial role in the growth of prostate cancer cells, and AR regulation is one of the important pathways." (PMID 31395805, 2019). "Interestingly, inhibition of CDK5 prevents prostate cancer cell growth, while drug-triggered CDK5 hyperactivation leads to apoptosis." (PMID 31395805, 2019). "In addition to cell growth, we also claimed that CDK5 is responsible for the apoptosis of prostate cancer cells under the status of drug-triggered “hyperactivation,” which is similar to in AD." (PMID 31395805, 2019). "This demonstrated that CDK5 may phosphorylate AR via direct biochemical interaction in prostate cancer cells by manipulation of CDK5 with overexpression, knockdown, and drug-targeted inhibition." (PMID 31395805, 2019). "Furthermore, our study demonstrated that CDK5 and p35 are positively correlated with the in vitro and in vivo growth of prostate cancer cells through AR regulation." (PMID 31395805, 2019). "To clarify the regulatory role of CDK5 and p35 in male reproduction and understand the relationship between CDK5 and prostate cancer, we demonstrated that human chorionic gonadotrophin (hCG), which is involved in major reproductive processes, regulates CDK5–p35 activity in rodent Leydig cells." (PMID 31395805, 2019). "Based on the multiple roles of AR in prostate cancer, CDK5 might be one of the relevant regulators in the cancer progression; this is discussed in the following section." (PMID 31395805, 2019). "Moreover, Calpeptin, an inhibitor of the p35 protein cleavage enzyme Calpain, significantly reverses RA-induced p25 overactivation of CDK5 while p35 protein expression is maintained in human prostate cancer cells and RA-triggered apoptosis is also prevented." (PMID 31395805, 2019). "One of our previous studies indicates the involvement of CDK5 in prostate cancer growth through negatively regulating p21CIP1, a member of the CDK inhibitor family containing conserved N-terminal regions for CDK binding, which suppresses cell cycle progression." (PMID 31395805, 2019). "Furthermore, treatment with siRNA of CDK5 or inhibitors reduced Digoxin-triggered prostate cancer cell death, suggesting that CDK5 plays an essential role in Digoxin-triggered prostate cancer cell death." (PMID 31395805, 2019). "In addition to growth regulation, CDK5 has been known as a regulatory protein that controls cytoskeletal remodeling, cell polarity, cell motility, and metastasis of prostate cancer cells." (PMID 31395805, 2019). "According to these observations, we believe that CDK5 may also play an important role in the clinical events of prostate cancer progression." (PMID 31395805, 2019).
prostate carcinoma (continued). "Among them, we found that gene CDK5 has isoform switching between prostate cancer and benign tissues, which may affect cancer development by changing androgen receptor (AR) phosphorylation." (PMID 30367578, 2018). "In addition to its role in brain tissues, CDK5 plays a key role in various types of cancer, including gastric cancer, prostate cancer, and lung cancer." (PMID 29312535, 2017). "In addition, emerging evidence indicates that CDK5 functions in prostate cancer cells through the control of cell-motility and metastatic potential." (PMID 29312535, 2017). "Finally, phosphorylation of androgen receptor by CDK5 plays a role in driving prostate cancer growth." (PMID 26509276, 2015). "CDK5 also showed to promote prostate cancer cell growth through androgen receptor." (PMID 26205145, 2015). "In the present study we screened the JHDL for compounds that differentially inhibit cancer cell growth in the presence of CDK5 inhibition; tilorone and a tilorone analog were identified as agents that selectively target CDK5-deficient PC3 prostate cancer cells." (PMID 24841903, 2014). "Some reports suggest that CDK5 may have a significant role in the regulation of breast, lung, and prostate cancer cell proliferation, apoptosis, migration, and invasion." (PMID 24966803, 2014). "As regards androgen stimulation, our previous report indicates the role of Cdk5 in androgen production in male testis, which implies that Cdk5 regulation of systemic androgen secretion may contribute to androgen-dependent prostate cancer growth." (PMID 23304206, 2012). "The previous studies also show that Cdk5 may contribute to the regulation of proliferation in thyroid cancer and prostate cancer." (PMID 23304206, 2012). "Involvement of Cdk5 in growth of breast and prostate cancers cells has been reported." (PMID 20673369, 2010). "Further, CDK5 controlled cell growth, migration and metastasis, and was indirectly involved in the regulation of cell cycle, which might contribute to the development of prostate cancer." (PMID 27406233, 2016). "Therefore, we hypothesize that Cdk5 might modulate both proliferation and apoptosis of prostate cancer cells and the activation status of Cdk5 might determine the different cell fates." (PMID 23304206, 2012). "Of most interest to us, due to potential novelty for treating phenotypic plastic prostate cancer, were the cell cycle–related CDKs, which included CDK2, CDK5, and CDK7." (PMID 39113611, 2024). "Other groups also reported that inhibition of CDK5 activity in MTC and prostate cancer cell lines decreased cell proliferation." (PMID 31910742, 2020). "Our study was the first to demonstrate the interaction between CDK5 and STAT3 Ser-727 phosphorylation in prostate cancer cells and regulates cancer growth." (PMID 31395805, 2019). "Thus, CDK5 and p35 are essential proteins in male reproduction, and the interaction between CDK5–p35 and StAR protein might be a potential monitoring target in androgen-related diseases, which is an important issue for prostate cancer." (PMID 31395805, 2019). "The blocking of CDK5 activity by its small interfering RNAs (siRNA) or Roscovitine, a pan-CDK inhibitor, reduces the cellular AR protein level and triggers the death of prostate cancer cells." (PMID 31395805, 2019). "Since CDK5 regulates both STAT3 and AR activation, it is important to further understand the detailed mechanism of this regulation in prostate cancer cells." (PMID 31395805, 2019). "Since it has been reported that CDK5 can interact with several important proteins in cancer progression, we also demonstrated that CDK5 has a direct protein-protein interaction with STAT3 in prostate cancer cell growth." (PMID 34207842, 2021).
prostate carcinoma (continued). "Based on our results, CDK5 activation promotes the growth of prostate cancer cells by direct interaction with STAT3 through Ser-727 phosphorylation, while CDK5-mediated STAT3 activation contributes to full AR transactivation in addition to CDK5-dependent Ser81-AR regulation." (PMID 31395805, 2019). "Interestingly, CDK5-dependent p21CIP1 degradation resulted in subsequent CDK2 activation in the nucleus, which promotes prostate cancer growth." (PMID 31395805, 2019). "In prostate cancer cells, Cdk5 promotes cell growth in an androgen receptor (AR)- independent way and maintains high AKT kinase activity, which is known to correlate with prostate cancer progression and considered as a critical growth-promoting pathway in prostate cancer cells." (PMID 28288624, 2017). "Further studies are needed to unravel the exact mechanism of action by which tilorone selectively targets CDK5-negative prostate cancer cells." (PMID 24841903, 2014). "Moreover, CDK5 is also a positive regulator to cell proliferation through STAT3 activation and STAT3-mediated androgen receptor (AR) activation via the phosphorylation of STAT3 at Ser727 in prostate cancer." (PMID 33396266, 2020). "Also, retinoic acid may inhibit the proliferation of prostate cancer cells through reducing the methylation level of the HOXB13 gene and the Cdk5-dependent p27 expression." (PMID 25520935, 2014).